IL4 (interleukin 4)
Diseases named in the same sentence as IL4 in open-access papers (continued):
Sharing a sentence is not in itself a finding about the gene and the disease.
tumor (continued). "Hepatic leptin was higher, while IL-4 was lower in the Tumor group compared to all other groups." (PMID 36834959, 2023). "Th2 cells produce IL-4 and IL-10 and favor tumor growth by inhibiting the host immune system." (PMID 37894300, 2023). "Exogenously administered IL-33 increased the expression of alarmins, Th2 chemokines (CCL17 and CCL22), CD8 + T cell chemokines (CXCL10, CX3CL1), eosinophil chemokines (CCL11, CCL13, CCL24), as well as Th2-related cytokines (IL-4, IL-13) and Th1 effector molecules (granzyme B) in the primary tumor." (PMID 37587450, 2023). "The wound healing assay results showed that after 24 and 48 hours, the scratch width of CRC cells co-cultured with IL-4-treated macrophages was apparently smaller than that in control group, indicating that the migration rate of tumor cells to the center of scratch increased significantly." (PMID 36776333, 2023). "Elevated IL‐4 and miR‐324‐5p levels in tumour microenvironment caused a decreased expression level of CUEDC2 in tumour‐associated macrophages, which resulted in excessive levels of proinflammatory cytokines, such as TNF‐α and IL‐6, and linked with both colitis and colon carcinogenesis." (PMID 37138536, 2023). "By contrast, other studies speculate that MCs may promote inflammation, inhibition of tumor cell growth, and tumor cell apoptosis by releasing mediators such as IL-1, IL-4, IL-6, IL-8, Mcpt3, Mcpt4, INF-y, TNF-α, TGF-β, LTB4, and chymase." (PMID 37686555, 2023). "The effectiveness of this approach was shown in a study in which intracavitary administration of pan-ErbB/IL-4 CAR T cells targeting patient-derived MPM xenografts in severe combined immunodeficient (SCID) mice showed significant tumor regression and cure in all mice." (PMID 37420216, 2023). "IL-4 also promoted tumor cell survival by making them resistant to apoptosis." (PMID 37835465, 2023). "In OSM-knockout mice, cSCC tumor volume was reduced by approximately 30% when compared to wild-type mice after one month, however there were still significant amounts of IL-6, IL-1β, IL-23α, CXCL1, IL-4, and IFNγ present in the tumor tissue compared to normal skin." (PMID 37841259, 2023). "In a mouse model of metastatic ovarian cancer, ABC transporters mediated membrane cholesterol efflux from TAMs, polarizing TAMs into tumor-promoting M2 phenotype, promoting IL-4-associated immunosuppression and invasive metastasis and inhibiting IFN-γ-induced anti-tumor effects." (PMID 37004014, 2023). "The mechanisms driving this phenotype could be related to IL-4, which promotes the infiltration of macrophages and eosinophils into the tumor site." (PMID 36980536, 2023). "In addition, MCs actively participate in tumor cell clearance and tumor rejection through the release of IL-1, IL-4, IL-6, and TNF-α." (PMID 37275909, 2023). "In the case of IL-4, preclinical studies indicate that supraphysiologic levels of exogenous IL-4 may induce tumour rejection, while endogenous IL-4 typically promotes tumour progression." (PMID 37455828, 2023). "In addition to the usual inducers, protein kinase N2 (PKN2) protein kinase is equally capable of inducing DUSP6 in tumor-associated macrophages, reducing ERK activity and the anti-inflammatory cytokines IL-4 and IL-10." (PMID 38139370, 2023). "Whether altered leptin and/or IL-4 in tumor animals had any effect on hepatic TG and PL alterations needs to be verified in future studies." (PMID 36834959, 2023). "However, exposure to anti-inflammatory stimuli in the tumour microenvironment (such as IL-4 and IL-10) induces a specific M2-like phenotype of macrophages that promotes tumour cell proliferation, invasion, angiogenesis, and metastatic spread." (PMID 36900335, 2023). "Tumor cells could promote the transition of macrophages from the M1 to the M2 subtype by secreting cytokines, such as interleukin-4 (IL-4) and transforming growth factor-beta (TGF-β)." (PMID 37371331, 2023).
tumor (continued). "Infiltrated immune cells shift their phenotypes from anti-tumor, also known as pro-inflammatory phenotypes, to pro-tumor phenotypes because tumor cells increase interleukins and chemokines such as IL-2, IL-4, IL-6, IL-7, IL-10, IL-12, and CXCL12 concentrations." (PMID 37533070, 2023). "IL-4 selectively induces apoptosis in these tumor cells in a Stat6-dependent manner in vitro and in vivo, therefore, treatments that induce upregulation of these cytokines, such as Esperanza extract, could be considered therapeutic alterations." (PMID 37629156, 2023). "Additionally, IL-4 can directly impact tumor proliferation and indirectly polarize TAMs to an M2-biased phenotype, thereby promoting tumorigenesis and growth." (PMID 37213667, 2023). "In our study, the marked upregulation of IL-4, traditionally associated with T-helper 2 (Th2) immune response and not an anti-tumor response, was an unexpected finding." (PMID 38203396, 2023). "Among them, M2 is the phenotype that exerts suppressive inflammatory overreaction and negative immunomodulatory effects, which can be polarized into M2a, M2b, M2c, and M2d subtypes when stimulated by IL-4/IL-13, LPS/immunocomplexes, IL-13/TGF-β, and tumor-associated factors, respectively." (PMID 37283946, 2023). "Several studies demonstrated that activated basophils can secrete different cytokines involved in PCa including IL-4, which promotes tumour-promoting Th2 inflammation and M2 macrophage polarization related to a poor prognosis, IL-13, and tumour necrosis factor-alpha (TNF-α)." (PMID 38137361, 2023). "However, in recent years, an increasing number of clinical data suggest that IL-4 primarily plays a tumor-promoting effect in most tumors." (PMID 36936961, 2023). "The primary tumor also contains tumor-associated macrophages (TAM) that promote a “pro-tumor” environment by producing anti-inflammatory cytokines such as IL-10 and TGF-beta via the stimulation of IL-13 and IL-4." (PMID 36769180, 2023). "Whether hepatic levels of leptin and IL-4 are altered by the presence of a tumor and/or chemotherapy treatment is unknown." (PMID 36834959, 2023). "In the lung, however, it is still unknown whether IL4 signaling participates in metastatic seeding and growth of tumor cells, or whether its role is mainly restricted to the primary tumor and bone metastases." (PMID 36077870, 2022). "In addition to tumor cells, these cells produce growth factors, chemokines, and local cytokines, such as IL-10, VEGF, TGF-β, and IL-4 which stimulate tumor growth and proliferation." (PMID 36153626, 2022). "At the tumor site, BMDSCs also have the capacity to differentiate into angiogenesis-promoting endothelial cells, or TAFs as a source of extracellular protease expression, TGF-β, VEGF, CXCL-12, -14, -16, CCL2-5, IL-4 or IL-6, the collective interplay of which contributes to tumor progression." (PMID 34918208, 2022). "Furthermore, high tumor expression of IL-10 and IL-4 resulted in lower recurrence free survival (p = 0.000 for IL-10; p = 0.021 for IL-4)." (PMID 35255925, 2022). "The expression and secretion of IL-4 in tumor cells were regulated by various factors." (PMID 35996149, 2022). "Moreover, we have demonstrated that incorporating CD28 signaling in CAR MUC1 upregulated the immunosuppressive cytokines, IL-4 and IL-10, upon encountering the targeted tumor cells." (PMID 36457849, 2022). "In tumor tissue, IL-4R presented a decrease in tumor tissue, which could mean that IL-4 cannot palliate the inflammatory status present in tumor tissue, thus perpetuating it." (PMID 36139645, 2022). "Strikingly, PARP inhibition can mitigate the M2-inducing effects of IL-4, IL-10, and M-CSF and results in large, highly phagocytic macrophages with remarkable anti-tumor activity ex vivo, suggestive of direct reprogramming of tumor macrophages by PARP inhibition." (PMID 36223740, 2022).
tumor (continued). "For example, upon the high levels of tumor-derived lactate, high-expressed PD-L1 on the surface of tumor cells, or IL-4, IL-10, and TGF-β are present in TME, tumor-associated macrophages (TAMs) would polarize into the M2 phenotype, which plays a pro-tumor role." (PMID 36246629, 2022). "However, in tumor immune microenvironment, Macrophages M1 transform into M2 activated by interleukin-4, -10, -13 (IL-4, IL-10, and IL-13), colony-stimulating factor-1 (CSF-1), and tumor growth factor β (TGF-β)." (PMID 35432538, 2022). "Additionally, the secretion of IL-4 influences the tumor microenvironment by activating M2 macrophages, which leads to tumor immune escape, invasion, and metastasis." (PMID 35479514, 2022). "Cytokine secretion, such as interleukin-4 (IL-4), IL-5, IL-9, IL-13, and amphiregulin (Areg), by type 2 innate lymphoid cells (ILC2s) is indispensable for homeostasis, remodeling/repairing tissue structure, inflammation, and tumor immunity." (PMID 35592688, 2022). "Experimental IL-25-signaling blockade (using the D9.2 clone which also blocks human IL-25R) inhibited ILC2 production of IL-4 and IL-13, limiting the suppressive capacities of MDSCs, thereby permitting the liberation of anti-tumor T cell and IFNγ-mediated immunity and reduced CRC." (PMID 35658010, 2022). "IL-4 promotes tumor proliferation and increases the production of ROS." (PMID 36611932, 2022). "These two designs enable CAR-T cells to play a potent anti-tumor role in the IL-4-rich TME." (PMID 35392217, 2022). "Furthermore, the splenocytes from T-01-treated mice showed increased secretion of the immune-enhancing cytokines INF-γ, IL-2, and IL-4 and decreased secretion of tumor-suppressive IL-10." (PMID 35615265, 2022). "The results showed that IL-4/7 ICR could reverse the inhibitory effect of IL-4, and enhance the persistence and anti-tumor activity of T cells (maintaining Th1 phenotype)." (PMID 35392217, 2022). "Indeed, in 2020, a study carried out in mice, reported that the reestablishment of IL-12 expression, involving a previous IL-4 blockade, by a new subset of regulatory DCs resulted in a tumour control, due to enhancement CD8+ T cell function." (PMID 35406451, 2022). "Additionally, IL-4, IL-5, and IL-13 have been demonstrated to accelerate tumor proliferation and metastasis." (PMID 35546682, 2022). "However, the tumor microenvironment is usually infiltrated by M2 cells arising from the influence of IL-4, IL-10 and IL-13." (PMID 35741450, 2022). "Interestingly, cytokines produced by classical pro-tumor immune cells such as Tregs, which produce IL-10 and IL-35; Th17 cells, which produce IL-17 and IL-22; or Th2 cells with IL-4, are all pro-angiogenic factors." (PMID 35626056, 2022). "Consistent with a decreased β-adrenergic tone, UCP-1 protein content was reduced in iWAT and aWAT depots of LLC tumor-bearing IL-4ra-KO mice compared with WT depots, corroborating the conclusion that IL-4ra–dependent IL-4 activation of macrophages regulates sympathetic activity and WAT browning." (PMID 35210363, 2022). "Besides, JUB decreased TNF-α and IL-4, -6, and -10 levels in mice of groups C (tumor-bearing + JUB) and G (tumor-bearing + CUMS + JUB) as compared with the corresponding control groups B (tumor-bearing control) and F (tumor-bearing + CUMS)." (PMID 36254198, 2022). "However, IL-4 and IL-5 levels were consistently increased in tumour tissue slices compared to tumour-free slices from patient-matched surrounding tissue, with an average fold change of 24.80 and 15.43, respectively." (PMID 35909511, 2022). "Th2 cells generate IL-4 and IL-10, which promote tumor growth by inhibiting the host immune system." (PMID 36204318, 2022). "IL-4 may have both tumour promoting and antitumour effects depending on the molecular and cellular environments, its sources, expressing time and dose." (PMID 36189228, 2022).
tumor (continued). "The IL4 release was significantly higher in DCs pulsed with tumor cells than with lysate, indicating a Th2 response going along with the slightly lower cytotoxic activity of T cells pulsed with tumor cells than with lysate (see Section 3.4)." (PMID 35684322, 2022). "Genetic overexpression of IL-33 led to increased tumour burden and expression of Il4, Il5 and Il13 in Th2 cells, and this correlated with increased tumorigenesis in the Apcmin/+ mice, while genetic deficiency of IL-33 reduced overall tumour Il4 and Il13 expression." (PMID 36263033, 2022). "Already in the early 1990s there were studies reporting that IL-4 might also have tumor-limiting functions, by suppressing IL-1-induced proliferation of AML cells." (PMID 36248849, 2022). "We used 10 ng/mL IL-4 to establish a tumor-like status with a high expression of M2 macrophages." (PMID 35178457, 2022). "To date, a comprehensive analysis focusing on the effects of the different tumor cell line-derived condition media (TU-CM) on the phenotype and function of the DCs differentiated in the presence of IL-4 and GM-CSF is unknown yet." (PMID 36194602, 2022). "The TME of the SHH-MB subgroup was studied by mosaic analysis with double markers, and it was found to contain astrocytes active in secreting IL4, in turn stimulating IGF1 production by tumor-associated microglia, whose metabolic signalling was involved in MB progression." (PMID 36005596, 2022). "When tumor cells are in low oxygen and low pH, they will release Neuropilin-1 (Nrp-1), TGF-β, IL6, IL4, Tim-3 to promote the transformation of macrophages into M2 type, which can help tumor cells to escape immune and secrete growth factors to enhance tumor growth." (PMID 36684237, 2022). "In contrast, pathways associated with tumor promotion and immunosuppression were enriched in TAMs such as arachidonic acid metabolism, matrix metalloproteinase (MMP), the vascular endothelial-derived growth factor (VEGF), IL-4, -10, -13 and PD-1 signaling." (PMID 36685571, 2022). "Similarly, IL-4 is involved in activating NK cells, which play a leading role in tumor apoptosis activation." (PMID 35589776, 2022). "Our IPA and GO analyses further showed that in the tumor infiltrating CD11b+ cells, several tumor promoting and immune suppressive pathways are enriched and mobilized, including ‘tumor microenvironment pathway’, IL-10/IL-4/TGFb signaling, T cell exhaustion pathway." (PMID 36439171, 2022). "Consistently, targeting IL-4 and IL-5 antibodies was reported to suppress tumor progression in multiple cancers, showing targeting Th2 cytokines might be a potential therapy for tumor treatment." (PMID 36564797, 2022). "Based on these findings, we next sought to identify whether there was a source of IL4 within PDAC tumours and whether this may also be regulated by FAK." (PMID 36138073, 2022). "The bioluminescence intensity of Arg1EP-Luciferase-GFP/Raw264.7 cells also increased significantly when cultured in the presence of IL-4 compared to the untreated controls, while bioluminescence intensity of Arg1 macrophages co-incubated with Hepa1-6 was the strongest in the tumor microenvironment." (PMID 35251971, 2022). "IL4 signaling in monocytes could have had a role during tumor cell survival in circulation, via extravasation as our eTEM suggests, or in seeding, dormancy or subsequent growth, all of which could translate into a reduced foci number." (PMID 36077870, 2022). "Extensive evidence has documented that shifting Th1/Th2 balance toward to Th2 polarization may contribute to the tumor immune escape, while IL-12 can suppress Th2 differentiation and promote Th1 production and the case in IL-4 is the opposite." (PMID 36601127, 2022). "M2 macrophages are involved in tumour progression and invasion, as they are mainly identified in early inflammatory infiltrate, being stimulated by Th2 cells and anti-inflammatory stimuli (IL-4, IL-10, IL-13, or monocyte colony-stimulating factor—M-CSF)." (PMID 35334544, 2022).
tumor (continued). "Similarly, IFN-γ promotes polarization of macrophages to M1 anti-tumor phenotype, while the presence of cytokines, such as interleukin (IL)-4, IL-10 and IL-13 stimulate M2 TAMs with pro-tumor phenotype." (PMID 35268568, 2022). "Yet, in hematological cancers, a tumor-promoting role of IL-4 is controversial." (PMID 36248849, 2022). "Subsequent research in mouse models of cancer indicated in primary tumors that IL4 is an essential cytokine responsible for macrophage differentiation to support a state that promotes macrophage-enhanced tumor cell invasion and thus tumor malignancy." (PMID 36077870, 2022). "Moreover, Th2 and Th17 helper lymphocytes secrete numerous cytokines (including IL-4, IL-5, IL-13, IL-17, IL-21 and IL-22) that contribute to increased tissue inflammation and thus stimulate tumor growth." (PMID 35741450, 2022). "Additionally, CCL2 has been reported as potently attracting BMDSCs, such as TAMs, to the tumor site and have the capacity to upregulate cathepsin expression based on their responsiveness to IL-4, -6 and -10 stimulation." (PMID 34918208, 2022). "Treatment with 5-aza-dC and TSA synergistically decreased the mRNA levels of M2 cytokines (il-10, il-4, and tgfb) and a marker (arg1) in tumor tissues, while increasing those of M1 cytokines (il-12p40 and ifng) in tumor tissues, as compared to either therapy alone and in the saline-treated control." (PMID 36483544, 2022). "IL-4 and lactate enriched in the tumor microenvironment promote the M2 polarization of TAMs." (PMID 36483544, 2022). "Similar IL4 increase and M2 prevalence were found in the tumor microenvironment of cancer patients." (PMID 35736195, 2022). "However, in addition to IL-4, Tfh also produce IL-21, which has been shown to promote tumor killing when used in combination with anti-PD-1 or anti-CLTA-4 immunotherapy." (PMID 35493515, 2022). "Among them, TILs may interact with TAMs, for example, the CD4 T cell-secreted IL4 may be involved in the M1-M2 transition, thereby facilitating tumor escape." (PMID 35574386, 2022). "In contrast, M2 macrophages, which are stimulated by IL-4 and IL-13 (produced by T-helper 2 cells), play a critical role in tumor initiation, proliferation, metastasis, and immune evasion, and express anti-inflammatory elements, such as IL-10 and transforming growth factor (TGF)-β." (PMID 35844605, 2022). "Moreover, the LDhi HCC cell line expressed a higher level of type II IL-4 receptor, which promoted tumor proliferation through binding IL-4 or IL-13." (PMID 35721518, 2022). "Since WT macrophages stimulated with IL4 showed an increased level of Cxcr2 transcripts, it was determined whether increased levels of CXCR2 induced by IL4 mediate the IL4-dependent increased transendothelial migration of tumor cells." (PMID 36077870, 2022). "Tumor M-MDSCs expressed Arginase 1 (Arg1), consistent with a suppressive phenotype, and the genes encoding the IL-4Rα and IL-13Rα1 receptor subunits, suggesting their potential ability to respond to ILC2-derived cytokines IL-4 and IL-13." (PMID 35658010, 2022). "Furthermore, Th2-derived cytokines such as IL-4 and IL-13 promote tumor progression by inducing M2 macrophage polarization." (PMID 35769911, 2022). "The 24-month overall survival probability in a cohort of patients with high gene expression versus low gene expression of listed chemokines in tumor specimens was 0.2 vs. 0.35 for IL-4, 0.2 vs. 0.35 for IL-10, 0.2 vs. 0.4 for CCL2, 0.2 vs. 0.57 for GM-CSF, and 0.15 vs. 0.23 for VEGF." (PMID 35884700, 2022). "Searching for lipolysis activation pathways that are independent of the β-adrenergic–cAMP–protein kinase A (PKA) signaling cascade, we found increased TNFα and iNos mRNA expression levels in iWAT of LLC-bearing IL-4-ra-KO animals compared with tumor-bearing WT mice." (PMID 35210363, 2022). "IL-4, but also the IL-13 pathways, were previously shown to promote tumor growth." (PMID 36275666, 2022).